BCL2L11 (BCL2 like 11)
Diseases named in the same sentence as BCL2L11 in open-access papers (continued):
Sharing a sentence is not in itself a finding about the gene and the disease.
pancreatic cancer (7 papers, 2012 to 2022). "Moreover, the observed association that rs36018702-A (correlated with rs590097-T) showed increased risk of PDAC is consistent with the higher expression of BCL2L11 in pancreatic cancer tissues than in normal pancreas tissues found through GEPIA2." (PMID 34926279, 2021). "In studies with pancreatic cancer cell lines, BCL2L11 has been correlated with apoptotic resistance as well as with metastatic potential." (PMID 22894607, 2012). "The result of the PPI network projected four genes (KIT, CDKN1B, RUNX2, and BCL2L11) as hub genes in pancreatic cancer, which may be possible targets of miR-221-3p." (PMID 32943991, 2020). "Taken together, the results show that miR-221-3p may act as an underlying tumour marker for prognosis prediction in pancreatic cancer and may work by acting on KIT, CDKN1B, RUNX2, and BCL2L11 expression." (PMID 32943991, 2020). "In addition, we examined the hub genes KIT, CDKN1B, RUNX2, and BCL2L11, which may act in pancreatic cancer, and confirmed that the expression of KIT, CDKN1B, RUNX2, and BCL2L11 is indeed affected by miR-221-3p." (PMID 32943991, 2020). "Thus, miR-221-3p may affect the incidence and development of pancreatic cancer by affecting KIT, CDKN1B, RUNX2, and BCL2L11 expression." (PMID 32943991, 2020).
acute myeloid leukemia (6 papers, 2014 to 2025). Acute myeloid leukemia (AML) is a group of neoplasms arising from precursor cells committed to the myeloid cell-line differentiation. "In acute myeloid leukemia (AML) cell, ectopic transfection of synthetic miR-29b can up-regulate the pro-apoptotic genes, such as BIM (BCL2L11) and the tumor suppressor programmed cell death-4 (PDCD4)." (PMID 27391030, 2016).
endometriosis (6 papers, 2014 to 2023). The growth of functional endometrial tissue in anatomic sites outside the uterine body. "The overexpression of LINC00261 inhibited the proliferation and invasion of the endometriosis cell line CRL-7566 through the BCL2L11 network." (PMID 34638965, 2021). "The role of BCL2L11 in endometriosis was investigated by siRNA knockdown." (PMID 34638965, 2021). "Moreover, LINC00261 competes with miR-132-3p to regulate the expression of BCL2L11 in endometriosis." (PMID 33302562, 2020). "BCL2-like 11, a member of the BCL-2 family, is involved in apoptosis, and suppresses invasion in endometriosis by promoting the epithelial-mesenchymal transition." (PMID 33901012, 2021). "LINC00261 directly binds to miR-132-3p to regulate BCL2L11 expression, which inhibits the proliferation and invasion of endometriosis cells, suggesting that LINC00261 plays an inhibitory role in the occurrence and development of endometriosis." (PMID 37455911, 2023).
ischemia (6 papers, 2013 to 2024). A hypoperfusion of the BLOOD through an organ or tissue caused by a PATHOLOGIC CONSTRICTION or obstruction of its BLOOD VESSELS, or an absence of BLOOD CIRCULATION. "miR-19b-1 targets the pro-apoptotic Bcl-2 family gene (Bcl2l11/BIM), reducing its mRNA and protein levels, thereby reversing ischemia-induced HF by inhibiting myocardial cell apoptosis." (PMID 39564110, 2024). "ChIP sequencing analyses also showed that FoxO1 binding to the promoter of pro-apoptotic genes, including Bcl2l11, Fadd, Bnip3, and Pmaip1, was decreased in the presence of ischemia or in C/EBP-β-KI, without concomitant increases in C/EBP-β binding to the promoter." (PMID 39060225, 2024).
breast tumors (5 papers, 2013 to 2024). "Finally, we analyzed the mRNA expression of ATG2B, BCL2L11, and c-Kit in 113 pairs of breast tumor and adjacent normal tissue samples obtained from the TCGA database." (PMID 38690279, 2024). "On the other hand, the splicing factor SRSF1 has been observed to be upregulated in breast tumors acting as an oncogene by producing impaired splicing isoforms of the pro-apoptotic genes BCL2 Like 11 (BIM) and the Bridging integrator 1 (BIN1) which are involved in the tumoral phenotype." (PMID 32635183, 2020).
Burkitt lymphoma (5 papers, 2009 to 2019). A rare form of malignant mature B-cell non-Hodgkin lymphoma. "In addition, the pro-apoptotic gene BCL2L11 (Bim) has been described to be repressed by EBNA-3A and EBNA-3C expression in the context of EBV negative Burkitt's lymphoma cell lines." (PMID 19578441, 2009).
osteosarcoma (5 papers, 2014 to 2024). A usually aggressive malignant bone-forming mesenchymal neoplasm, predominantly affecting adolescents and young adults.
Splenomegaly (5 papers, 2008 to 2021). Abnormal increased size of the spleen. "Bcl2l11−/−Faslpr/lpr and even Bcl2l11+/−Faslpr/lpr mice developed lymphadenopathy and splenomegaly at a dramatically increased magnitude and rate compared to mice lacking either apoptosis initiator alone." (PMID 18275830, 2008).
systemic lupus erythematosus (5 papers, 2014 to 2025). An autoimmune multi-organ disease typically associated with vasculopathy and autoantibody production. "By suppressing several targets involved in BCR signaling, such as growth arrest and DNA damage inducible alpha (GADD45A), phosphatase and tensin homolog (PTEN) and BCL2 like 11 (BCL2L11), upregulation of miR-148a promotes survival of immature B cells in a lupus mouse model." (PMID 30322050, 2018).
viral infection (4 papers, 2019 to 2023). "The lncRNA Morrbid and its locus have been shown to control CD8+ T cell expansion, survival and effector function during viral infection by regulating the pro-apoptotic factor Bcl2l11 (also known as Bim) and PI3K-AKT signaling strength." (PMID 37346034, 2023).
Alzheimer disease (3 papers, 2014 to 2022). A progressive, neurodegenerative disease characterized by loss of function and death of nerve cells in several areas of the brain leading to loss of cognitive function such as memory and language. "For example, inhibition of BCL2L11 reduces neuron apoptosis in Alzheimer's diseases." (PMID 35799645, 2022).
chronic lymphocytic leukemia (3 papers, 2011 to 2023). "BCL2L11 has been implicated in chronic lymphocytic leukaemia (rs17483466, P = 2.36×10−10) and follicular lymphoma (rs3789068, P for trend = 0.0004)." (PMID 21533175, 2011).
ischemic stroke (3 papers, 2019 to 2022). A stroke disorder caused by obstruction of blood flow to the brain, due to thrombotic (local blood clot formation) or embolic (due to a blood clot or other material traveling from another site) event. "GWAS also showed that variants in CDKN1A are associated with ischemic strokes, atrial fibrillation and cardioembolic stroke, while variants in other experimentally validated gene targets of mir-423-3p; PA2G4 are associated with BMI and BCL2L11 with T2DM and cholesterol levels." (PMID 36277770, 2022).
Lymphadenopathy (3 papers, 2008 to 2021). Enlargement (swelling) of a lymph node. "Thus, loss of Bim and Fas do not cooperate to cause abnormalities in the thymus, demonstrating that the enhanced lymphadenopathy and splenomegaly seen in Bcl2l11−/−Faslpr/lpr and Bcl2l11+/−Faslpr/lpr mice are a consequence of defects in peripheral lymphoid organs." (PMID 18275830, 2008).
Sepsis (3 papers, 2014 to 2022). Sepsis is defined as life-threatening organ dysfunction caused by a dysregulated host response to infection. "In contrast, the transcript levels of anti-apoptotic genes, such as BCL2L11 and BCL2L1, were upregulated only in the sepsis group, wherein that of BCL2 was downregulated in both the groups." (PMID 36443881, 2022). "Moreover, transcript levels of the pro-apoptotic genes BAK1, CYCS, BBC3, CASP7, and CASP8 were upregulated in the COVID-19 cohort, whereas those of anti-apoptotic genes, such as BCL2L11 and BCL2L1, were upregulated in the sepsis cohort." (PMID 36443881, 2022).
thyroid cancer (3 papers, 2015 to 2025). "Functional analysis to validate these candidate genes in thyroid cancer cells showed that one of the three, BCL2L11, has a tumor suppressor effect on proliferation and apoptosis." (PMID 40903906, 2025).
acute T-cell leukemia (2 papers, 2012 to 2016). "Moreover, a study identified PP2A (encoded by PPP2R5E) along with BIM (Bcl2L11), an AMP-activated kinase (encoded by Prkaa1), and the tumor suppressor phosphatase PTEN as the targets of miRNA-19 in Notch-induced acute T-cell leukemia cells." (PMID 22121480, 2012).
Buruli ulcer (2 papers, 2017 to 2021). "Buruli ulcer (BU) is a devastating skin mycobacterial infection characterized by extensive cell death, which was previously suggested to be mediated by Bcl2-like protein 11 (BIM, encoded by the BCL2L11 gene)." (PMID 33467983, 2021).
diabetic kidney disease (2 papers, 2011 to 2018). Progressive kidney disorder caused by vascular damage to the glomerular capillaries, in patients with diabetes mellitus. "Our results provide the first direct evidence that an alteration in the acetylation of a transcription factor (Foxo4) in the podocyte promotes the transcription of a pro-apoptotic gene, Bcl2l11 and contributes to podocyte loss, which is considered a key mechanism of diabetic nephropathy." (PMID 21858169, 2011).
endometrial cancer (2 papers, 2020 to 2022). Primary or metastatic malignant neoplasm involving the endometrium (mucous membrane that lines the endometrial cavity). "For example, BCL2L11 regulated by miRNA markers in UCEC, was proved to be differentially expressed between endometrial canceration and normal menstrual cycles (P < 0.0001)." (PMID 32523951, 2020).
heart failure (2 papers, 2021 to 2022). Inability of the heart to pump blood at an adequate rate to meet tissue metabolic requirements. "Intriguingly, silencing of BCL2L11 at least contributes to miR‐19b‐1 overexpression–mediated apoptosis reduction and heart failure amelioration." (PMID 35699193, 2022).
Obesity (2 papers, 2020 to 2024). Accumulation of substantial excess body fat. "However, with obesity, we observed increased accessibility of genes involved in cell cycle regulation (ATM, CDKN1C, BCL2L11), autophagy (HSPA8, IRF8, PEX5), and protein catabolism (CDC34, CTSB, UBB)." (PMID 39872537, 2024).
T cell lymphoma (2 papers, 2012 to 2016). "In regard to molecular mechanisms of TCF3 antitumor effects, in Sézary syndrome (a subtype of T cell lymphoma) derived cells, no significant cell death induction was observed after E47 overexpression, whereas, up-regulation of proapoptotic genes including BCL2L11 and BIK have been seen." (PMID 27166193, 2016).
triple-negative breast carcinoma (2 papers, 2016 to 2020). An invasive breast carcinoma which is negative for expression of estrogen receptor (ER), progesterone receptor (PR), and human epidermal growth factor receptor 2 (HER2). "In agreement with our data, PIP has been reported to inhibit the PI3K/AKT axis in human triple-negative breast cancer cells and to activate FOXO3, inducing the expression of the FOXO target gene BCL2 Like 11 (BIM) in HeLa cells." (PMID 33316942, 2020).
adenoma (1 paper, 2016). A neoplasm arising from the epithelium. "The commonly repressed genes in these two adenoma samples include BCL2L11, TP53INP2, HIST1H1C, TRPM6, MIR22HG, and MIR5047." (PMID 27100181, 2016).
Age-related cataract (1 paper, 2022). A type of cataract (opacification of the lens) that forms during the course of aging. "The finding revealed that down-regulation of lncRNA KCNQ1OT1 protected LECs from oxidative stress stimulated apoptosis via regulating the miR-124-3p/BCL2L11 pathway in age-related cataract." (PMID 35170373, 2022).
alopecia (1 paper, 2023). Hair loss usually from the scalp. "Alopecia GWAS identified CLEC16A, STX17, and BCL2L11/BIM as risk factors." (PMID 37175930, 2023).
ameloblastoma (1 paper, 2021). The most common odontogenic tumor, arising from the epithelial component of the embryonic tooth and usually affecting the molar-ramus region of the mandible or maxilla. "BCL2L11 is one of the most important regulators of apoptosis, and its transcription is likely to be regulated by promoter DNA methylation in ameloblastomas, which may affect the biologic behavior of this neoplasm." (PMID 33680332, 2021).
cervical neoplasms (1 paper, 2025). "Additionally, miR-4428 is implicated in colonic and cervical neoplasms through regulatory interactions affecting BCL2L11 and PBX1 expression, respectively." (PMID 40282289, 2025).
cognitive decline (1 paper, 2021). "Its overexpression prevented Aβ deposition, cognitive decline, and reduced apoptosis rate of neurons by targeting BCL2L11." (PMID 33790780, 2021).
colon adenocarcinoma (1 paper, 2021). "The expression of ACTA2-AS1, miR-4428 and BCL2L11 in colon adenocarcinoma tissues were detected via qRT-PCR." (PMID 33845844, 2021). "Our data demonstrated that ACTA2-AS1 could suppress colon adenocarcinoma progression via sponging miR-4428 to regulate BCL2L11 expression." (PMID 33845844, 2021).
colorectal adenocarcinoma (1 paper, 2017). The most common type of colorectal carcinoma. "MiR-32-5p was significantly decreased in fatty acids-treated human colorectal adenocarcinoma cells accompanied by a decrease in BCL-2 and BCL2L11 expression." (PMID 29225772, 2017).
deafness (1 paper, 2020). An inherited or acquired condition characterized by the complete loss of the ability to hear from one or both ears. "Among them were four genes associated with deafness [grainyhead like transcription factor 2 (GRHL2), BCL2 like 11 (BCL2L11), ELMO domain containing 3 (ELMOD3), usherin (USH2A)]." (PMID 32835229, 2020).
endometrial adenocarcinoma (1 paper, 2021). "In human endometrial adenocarcinoma, miR-106a mimics co-transfected with wild-type BCL2L11 3′-UTR markedly inhibited the relative luciferase activities of RL95-2 and HEC-1B cells, suggesting that BCL2L11 is the direct target of miR-106a." (PMID 33845844, 2021).
Hepatic fibrosis (1 paper, 2025). The presence of excessive fibrous connective tissue in the liver. "Down-regulation of several miRNAs (ssc-miR-363, ssc-miR-222, and ssc-miR-106a) targeting mRNAs coding for anti-apoptotic mitochondrial genes (BCL2L11 and BCL2L1) was also observed and suggests a reduction in cellular toxic insult and death corresponding to a reduction in hepatic fibrosis." (PMID 40040391, 2025).
hypereosinophilic disorders (1 paper, 2022). "Specifically, this publication stated that the long non-coding RNA Morrbid regulates the transcription of the pro-apoptotic gene BCL2L11 (BIM) in an antidromic manner and that Morrbid is significantly upregulated in patients with hypereosinophilic disorders." (PMID 34654952, 2022).
Hyperinsulinemia (1 paper, 2023). An increased concentration of insulin in the blood. "BCL2L11 (FCHG, ins = 1.16), CDKN1A (FCHG, ins = 0.97) and TIMP2 levels (FCHG, ins = 1.50) were not affected by hyperinsulinemia." (PMID 37313172, 2023).
hypopharyngeal carcinoma (1 paper, 2025). Carcinoma, predominantly squamous cell, arising from the epithelial cells of the hypopharynx. "The results showed that the expression levels of FOS (an MAPK pathway-related gene), SERPINE1 (a TGF-β pathway-related gene), and BCL2L11 (a FoxO pathway-related gene) were significantly higher in hypopharyngeal carcinoma tissues than in adjacent non-tumor tissues." (PMID 40649749, 2025).
nasopharyngeal carcinoma (1 paper, 2014). A carcinoma arising from the nasopharyngeal epithelium. "Transgenic over-expression of BCL2L11 isoforms in EBV infected B cells or nasopharyngeal carcinoma cells enhance apoptosis of these cells." (PMID 24651368, 2014).
pharynx tumors (1 paper, 2015). "Interestingly, we noticed upregulation of BCL2L11, the known apoptotic pathway gene, in the larynx tumors and downregulation of FOXC2 gene, involved in EMT pathway, in the pharynx tumors only." (PMID 25575813, 2015).
retinal degeneration (1 paper, 2023). Degeneration of the retina. "BCL2L11 up-regulation contributes to RGC injuries during retinal degeneration." (PMID 37819813, 2023).
rheumatoid arthritis (1 paper, 2025). A chronic, systemic autoimmune disorder characterized by inflammation in the synovial membranes and articular surfaces. "We uncover BCL2L11 as the probable causal gene within the rheumatoid arthritis (RA) locus rs13396472, despite the GWAS variants’ intronic positioning relative to ACOXL, and we identify mechanisms involving SESN3 dysregulation in the RA locus rs4409785." (PMID 39930543, 2025).
Stem cell leukemia/lymphoma (1 paper, 2021). "miR-339-5p via downregulation BCL-2L11 and Bax could promote development of Stem cell leukemia/lymphoma (SCLL) syndrome." (PMID 34368145, 2021).
thymic tumors (1 paper, 2023). "Consistent with the oncogenic role of AKT, FOXO target genes include tumor-suppressive genes (BCL2L11(Bim), BBC3(PUMA), CDKN1B(p27Kip)), and overexpression of FOXOs induces apoptosis and cell cycle arrest, while suppression of FOXOs promotes tumorigenesis in prostate, gastric, and thymic tumors." (PMID 37773170, 2023).
type 2 diabetes (1 paper, 2015). "Islets isolated from organ donors with type 2 diabetes had elevated mRNA expression of the pro-apoptotic BH3-only molecules BIM (BCL2L11) and PUMA (BBC3), highlighting that their activation is cell type and stimulus-specific." (PMID 26137578, 2015).